PTH (parathyroid hormone)
Diseases named in the same sentence as PTH in open-access papers (continued):
Sharing a sentence is not in itself a finding about the gene and the disease.
osteoporosis (continued). "Conversely, there are few existing anabolic bone therapeutics for osteoporosis including, parathyroid hormone (PTH) and, recently, Romosozumab, a humanized-neutralizing monoclonal antibody against sclerostin, an antagonist of Wnt signaling secreted by an osteocyte." (PMID 32325749, 2020). "Literatures about combination PTH and antiresorptive drugs for osteoporosis." (PMID 33584284, 2020). "Some patients with diagnosis of osteoporosis also had fibrous osteitis, with high serum PTH levels, which may explain at least partially, the occurrence of bone pain in patients with the diagnosis of osteoporosis." (PMID 32756862, 2020). "If changes in bone quality following PTH administration can improve the outcome of dental implant treatments, it may be possible to use PTH during dental implant treatment for osteoporosis patients." (PMID 31142769, 2019). "Parathyroid hormone (PTH) is used to treat osteoporosis, but its therapeutic mechanism remains unclear." (PMID 30902975, 2019). "A clinical dose of PTH to treat human osteoporosis is 20–40 μg daily in Japan and the USA." (PMID 31783887, 2019). "Subsequent evaluation of patients with osteoporosis further confirmed that PTH increases BMD in the spine and femur of men and women more efficiently than treatment with bisphosphonates, and decreased the risk of vertebral and nonvertebral fractures by more than 50%." (PMID 31565870, 2019). "Daily PTH administration is limited to 2 years or less for the treatment of osteoporosis in humans." (PMID 31844831, 2019). "The limitations of our work include a lack of information on other factors that may also contribute to osteoporosis, such as nutrition, calcium/vitamin D intake, and levels of parathyroid hormone and prolactin." (PMID 31019532, 2019). "In conclusion, we reported for the first time the importance of identified allelic combinations of SOST rs1234612, PTH rs7125774, FDPS rs2297480, and GGPS1 rs10925503 gene variants for evaluation of the individual resistance or sensitivity to BPs treatment of osteoporosis." (PMID 31437227, 2019). "Human parathyroid hormone (hPTH) is applied to the therapy of osteoporosis successfully, however, the mechanism, especially the signaling pathway activated in the healing fracture by PTH is still unknown." (PMID 30157832, 2018). "In addition, PTH-loaded MNs were found to effectively suppress decreases in bone density in a rat model of osteoporosis." (PMID 30400376, 2018). "Basic, translational, and clinical research over the past three decades has identified parathyroid hormone and its analogs as important bone anabolic drugs for osteoporosis and illuminated many of the cellular and molecular mechanisms through which these agents regulate bone remodeling." (PMID 30283888, 2018). "As a result of these findings, we suggest that our dissolving MNs composed of HA may have potential as transdermal formulations for efficient and safe PTH delivery for the treatment of osteoporosis." (PMID 30400376, 2018). "Intermittently administered human parathyroid hormone (PTH; fragment 1–34) can increase bone mineral density and reduce the risk of fracture in osteoporosis, though the underlying mechanism remains unclear." (PMID 30149605, 2018). "An abrupt rise in serum PTH may lead to a significant increase in serum calcium levels and trigger a hypercalcemic crisis; however, urolithiasis and osteoporosis cannot develop within a limited time." (PMID 30123260, 2018). "Parathyroid hormone (PTH), which has already been approved for the treatment of osteoporosis, could be also a therapy for bone healing defects." (PMID 30096765, 2018). "PTH is approved as a treatment for osteoporosis, but not for cancer-induced bone disease or bone loss caused by anti-cancer therapies." (PMID 30261597, 2018).
osteoporosis (continued). "Second, serological data on biomarkers associated with osteoporosis, such as vitamin D status, inflammatory cytokine levels, parathyroid hormone and homocysteine, were not available, due to the absence of measurements." (PMID 29665863, 2018). "In addition, the therapeutic potential of MNs to treat post-menopausal osteoporosis following the application of PTH-loaded MNs was assessed in a rat osteoporosis model." (PMID 30400376, 2018). "After each PTH cycle there is a net increase of high quality bone similar to that of younger individuals, predominantly at regions subjected to mechanical stress; hence its potency as an osteoporosis treatment." (PMID 30364287, 2018). "Teriparatide, a recombinant form of PTH, has been approved for use in women with osteoporosis." (PMID 29098361, 2018). "Thus, to clarify if the PLC signaling involved in the controversial functions of PTH administration would shed novel light on bone metabolism and osteoporosis treatment." (PMID 30157832, 2018). "In this study, intermittent PTH was administered to rats to treat OVX-induced osteoporosis." (PMID 28438150, 2017). "Intermittent parathyroid hormone (PTH) can be used to treat osteoporosis of the spine and hip." (PMID 28438150, 2017). "Although detailed information about medications was not collected, frequently recommended and prescribed medications for osteoporosis including bisphosphonate, calcium, and vitamin D might influence both PTH and vitamin D levels." (PMID 28384340, 2017). "While the long-term physiologic consequences of this are unclear, the established therapeutic roles of PTH and PTHrP in diseases like osteoporosis and cancer underscore the importance of understanding consequences of the RAMP2-PTH1R interaction in various organ systems in vivo." (PMID 28727763, 2017). "Our results suggest that continual intermittent PTH administration before and after dental implant placement is effective for the achievement of favorable stability and osseointegration in the presence of osteoporosis." (PMID 29069147, 2017). "Therefore, according to the change in the trabecular bone microarchitecture (i.e., the difference in BV/TV and TbTh), intermittent PTH effectively treated OVC-induced osteoporosis of the mandible." (PMID 28438150, 2017). "A significantly higher PTH in the women with osteoporosis as compared to controls was observed." (PMID 28121926, 2017). "Favorable effects of PTH on BMD and fracture risk are also reported in men with osteoporosis." (PMID 28246925, 2017). "The role of SIK2 and 3 in bone formation has been recently investigated in osteocytes in which it has been demonstrated that SIK inhibitors in vitro can mimic the effect of parathyroid hormone (PTH), the only approved osteoporosis treatment that stimulates new bone formation." (PMID 28973003, 2017). "Teriparatide (recombinant human parathyroid hormone 1–34) is increasingly used for the treatment of severe osteoporosis because it stimulates bone formation and may potentially enhance fracture healing." (PMID 28388910, 2017). "Intermittent PTH can be used to treat osteoporosis of the spine and hip." (PMID 28438150, 2017). "This study aimed to evaluate the effects of continual intermittent PTH administration before and after dental implant placement on primary stability and secondary stability in the presence of osteoporosis induced in rabbit models by ovariectomy and glucocorticoid administration." (PMID 29069147, 2017). "Osteoporosis of the femur or mandible in the rats was ameliorated by intermittent PTH therapy." (PMID 28438150, 2017). "Indeed, an evoked serumDKK-1 level was determined in RA patients as compared with healthy individuals, which was also found to correlate with parathyroid hormone, bone erosions, and osteoporosis." (PMID 28373995, 2017). "PTH is an osteoanabolic agent for osteoporosis patients, and it may affect sinus augmentation in individuals who have diseases that compromised bone." (PMID 28280735, 2017).
osteoporosis (continued). "Parathyroid hormone (PTH) is the most important endocrine regulator of the concentration of calcium (Ca2+) and phosphorus in extracellular fluid, and its concentration can act as a measure of osteoporosis and parathyroid disorders." (PMID 27694822, 2016). "PTH is currently the only approved osteoporosis therapy that promotes new bone formation." (PMID 27759007, 2016). "After adjusting for age, BMI, free thyroxine, 25(OH)D, PTH, smoking, drinking, and the period of menopause, women in the lower TSH tertile had a significantly greater risk of osteoporosis compared with the upper TSH tertile group (OR 1.86, 95% confidence interval [CI] 1.22-2.83, p < 0.01)." (PMID 28053824, 2016). "In addition to PTH treatments, we modeled the effects of other interventions, which are currently in use or being tested as a potential treatment for osteoporosis." (PMID 27379013, 2016). "Teriparatide arose as a systemic synthetic drug with the same amino acid sequence of the PTH active form, which is currently used as long-term treatment option for patients with osteoporosis; and this drug can interfere in a positive way in both sides (pressure and tension area)." (PMID 27957280, 2016). "In this population, the negative relationship between PTH and bone mineral content as found in older white people is absent, and the risk of osteoporosis and fragility fractures is lower than in white British older adults." (PMID 27294326, 2016). "Paradoxically, the same PTH, which in high concentrations may culminate within osteoporosis, may also enhance the longevity of osteoblasts, increasing the bone density through the elevation of bone turnover." (PMID 27957280, 2016). "Recombinant PTH is the only current osteoanabolic therapy approved for osteoporosis treatment." (PMID 27759007, 2016). "Oestrogen and PTH could alleviate spinal osteoporosis in ovariectomized rats and increase MCC volume in the endplate, thus improving disc nutrition supply and alleviating disc degeneration." (PMID 27279629, 2016). "PTH has been used successfully in the treatment of osteoporosis in humans." (PMID 26034928, 2015). "It is possible that improved therapeutic protocols for delivering PTH to treat osteoporosis could be designed employing short periods of Cox2 inhibition." (PMID 25781979, 2015). "Intermittent PTH was the first anabolic agent approved for osteoporosis therapy in the USA." (PMID 25781979, 2015). "Having divided the anti-osteoporosis drugs into bisphosphonates, parathyroid hormone (PTH) and others (such as vitamin D and raloxifene), we found that the proportion of patients treated with PTH was significantly higher in the BMD <70 % of YAM group (p = 0.008)." (PMID 26420629, 2015). "Lately, parathyroid human hormone (PTH) has been approved for the treatment of osteoporosis in two different presentations, 1-34 active fraction (Teriparatida, Forsteo®) and intact molecule (PTH, Protact®) identic to the natural complete hormone (and 84 aminoacid polypeptide)." (PMID 24608203, 2014). "PTH drugs are a standard anabolic treatment for osteoporosis approved by the FDA." (PMID 24465596, 2014). "Several anti-osteoporosis drugs such as strontium ranelate and parathyroid hormone (PTH) may support fracture healing as there are studies that have indicated their clinical benefits in promoting fracture healing in humans." (PMID 25526611, 2014). "The mice were treated with PTH1-34 (containing the first 34 residues of mature PTH), an anabolic drug currently used for treating osteoporosis, and compared with the vehicle-treated Bmi1-/- and wild-type littermates in terms of skeletal and haematopoietic phenotypes." (PMID 24705625, 2014). "In addition, LTG induces the secretion of parathyroid hormone (PTH) thereby modulating calcium homeostasis leading to osteoporosis." (PMID 24967313, 2014).
osteoporosis (continued). "The fracture HR between treatment groups remained consistent after the removal of subjects who initiated an effective osteoporosis therapy (eg, bisphosphonates, selective estrogen receptor modulators [SERMs], PTH) after the last dose of IP (HR 0.85; 95% CI, 0.40–1.79)." (PMID 23109251, 2013). "Apart from acting as an estrogen analogue, genistein might interact with PTH/PTHR1 during ovariectomy-induced osteoporosis." (PMID 22312238, 2012). "Further adjustment for PTH levels and osteoporosis did not affect the associations between 25OHD levels and this performance test." (PMID 22539952, 2012). "However, due to its high cost of treatment and adverse effects, such as marrow fibrosis, headache, and osteosarcoma, PTH should only be considered for men with severe osteoporosis." (PMID 22844328, 2012). "Biochemical markers of bone turnover may be useful aids for managing patients with osteoporosis along with a secondary objective measure of PTH action." (PMID 21857768, 2011). "Our current study suggests that combining treatments with PTH may abrogate dexamethasone-induced osteoporosis and act synergistically with proteasome inhibitors to stimulate bone formation and repair bone lesions in MM." (PMID 21188144, 2010). "Therefore the combination of OPG and PTH represents an effective therapeutic approach to treating or reversing severe osteoporosis in humans." (PMID 19747396, 2009). "At present, PTH is the most potent anabolic (as opposed to antiresorptive) agent available for clinical treatment of osteoporosis to reduce fracture risk." (PMID 19995322, 2009). "Parathyroid hormone (PTH) is a potent anabolic agent for the treatment of osteoporosis." (PMID 19851510, 2009). "Thus, the problem with accelerated osteoporosis in males exposed to alcohol seems to be related to calcium malabsorption with subsequent PTH elevation and low testosterone levels." (PMID 15706763, 1997). "Therefore, direct small molecule SIK2/SIK3 inhibitors may represent a strategy to mimic PTH actions to treat different forms of osteoporosis." (PMID 41908158, 2026). "However, the challenge in treating osteoporosis is the rapid bone loss that occurs after discontinuation of the bone anabolic treatment, and PTH is no exception." (PMID 41432314, 2026). "Currently, pharmacologic agents for osteoporosis are mainly divided into antiresorptive drugs to inhibit bone resorption and anabolic drugs to promote bone formation, including bisphosphonates, denosumab, teriparatide, calcitonin and low‐dose parathyroid hormone." (PMID 39823248, 2025). "Thus, Intermittent PTH administration might be considered as an available treatment modality for dental implants in osteoporosis patients." (PMID 40507663, 2025). "Additionally, diabetic bone disease and high PTH-induced osteoporosis might inter-connect in the same patient, while sarcopenia, as a complication of both ailments, represents a supplementary osteoporotic fracture risk (due to an increased risk of fall)." (PMID 40283231, 2025). "Thus, treatment with PTH analogs have the potential to treat osteoporosis and/or OA [29, 30••]." (PMID 38372871, 2024). "In conclusion, after in silico and in vitro analyses, we propose hsa-miR-146–5p, hsa-miR-346, hsa-miR-551b-5p, hsa-miR-338–5p and hsa-miR-186–5p as the most prominent miRNAs that could help further understand the mechanism of action of PTH on bone formation and osteoporosis." (PMID 39086902, 2024). "However, the present study provided a new perspective that RPD might result in osteoporosis by affecting galactose metabolism and parathyroid hormone synthesis, secretion, and action pathway." (PMID 39268461, 2024). "These new findings might lead to new treatment strategies; administration of anabolic agents such as teriparatide (a recombinant human parathyroid hormone) to enhance bone development, as is done in the treatment of osteoporosis and osteogenesis imperfecta might be considered." (PMID 39571160, 2024).
osteoporosis (continued). "Although parathyroid hormone agents are typically used in clinical trials, they have limitations in clinical use owing to different medicinal effects followed by changes in the concentration and lower efficacy compared to bisphosphonates, the typical osteoporosis drugs." (PMID 39062525, 2024). "Additionally, due to database constraints, it was not possible to adjust for all potential confounding variables, such as osteoporosis and parathyroid hormone levels, which may influence vitamin D levels and auditory health." (PMID 39131738, 2024). "Additionally, research on self-dissolving microneedle arrays for the delivery of PTH demonstrated high bioavailability and efficacy in treating osteoporosis in rat models, further establishing the versatility and clinical potential of microneedle patches for various medical applications." (PMID 39006724, 2024). "Hence, the upregulation of RAAS in T2D may stimulate the production of excessive amounts of PTH, leading to bone fracture and osteoporosis." (PMID 37569338, 2023). "Also, research into establishing a link between PTH patterns and other types of osteoporosis indicate that PTH modulation may be only a secondary effect, but that other catabolic bone regulators (such as RANKL) could directly be affected by the disease." (PMID 36996072, 2023). "However, the Malmo Osteoporosis Prospective Risk Assessment cohort, which included 1044 community-dwelling women who were aged >85 years and followed for 10 years, found that PTH was not independently associated with all-cause mortality." (PMID 36615752, 2022). "PTH is known to exert anabolic or catabolic effects depending on whether administration is intermittent or continuous; PTH description in our model is restricted to the anabolic administration regimes relevant for osteoporosis treatment." (PMID 35942681, 2022). "Consequently, levels of parathyroid hormone (PTH) usually increase to maintain the serum calcium levels, at the expense of calcium resorption from the bone, which may lead to osteopenia or osteoporosis status." (PMID 35893910, 2022). "Notably, intermittent administration of parathyroid hormone (PTH) is antagonistic to glucocorticoid-induced osteoporosis because it can enhance bone formation; PTH administration increased the cortical bone thickness and trabecular bone structure in osteoporotic rats." (PMID 35675357, 2022). "The anti-osteoporosis drugs were mainly bone resorption inhibitors (such as bisphosphonates, calcitonin, estrogens, selective estrogen receptor modulators), bone formation enhancers (parathyroid hormone) and others (active vitamin D and its analogs, vitamin K2, strontium salts)." (PMID 36193128, 2022). "CBPB was particularly associated with a decreased risk of osteoporosis in patients with longer hemodialysis vintage, lower serum albumin level, lower intact PTH level, and active vitamin D analog use as well as in non-CVD, non-diabetes mellitus, and non-PPI use patients." (PMID 33462371, 2021). "The pathway analysis demonstrated that both cancer, Cushing syndrome, Parathyroid hormone, Wnt/β-catenin and Hippo signaling pathways may play crucial roles in osteoporosis pathogenesis by the dysregulation of the osteoblastic and osteoclastic biological processes." (PMID 32269995, 2020). "This compound could reproduce all the effects of the original extract and even showed a therapeutic effect comparable to that of parathyroid hormone (PTH)—the only anabolic agent approved by the FDA for osteoporosis treatment —in a model of osteopenia in ovariectomized mice." (PMID 32131438, 2020). "Therefore, targeting a cell or molecule alone may be insufficient for the prevention of osteoporosis—a common shortcoming related to conventional drugs such as PTH or bisphosphonate." (PMID 33109775, 2020).